ZFHX2 (zinc finger homeobox 2)
Description:
Transcriptional regulator that is critical for the regulation of pain perception and processing of noxious stimuli.
Synonyms: KIAA1056; KIAA1762; ZNF409; ZFH-5; MARSIS; ZFH5
Tractability: No criterion of Open Targets' tractability assessment is met for any kind of drug.
Gene: Protein-coding gene on chromosome 14 (23,520,857 to 23,556,192, reverse strand). Ensembl gene ENSG00000136367.
Subcellular location: Nucleus
Subcellular location (Human Protein Atlas): Nucleoli fibrillar center; Nucleoplasm
Gene Ontology:
Molecular function: protein binding; DNA-binding transcription factor activity, RNA polymerase II-specific; RNA polymerase II cis-regulatory region sequence-specific DNA binding; DNA binding; nucleic acid binding; zinc ion binding
Biological process: regulation of sensory perception of pain; regulation of transcription by RNA polymerase II; regulation of DNA-templated transcription
Cellular component: nucleus; chromatin
Genetic constraint (gnomAD): Loss-of-function variants: 67 observed, 135.99 expected, observed/expected ratio (o/e) 0.49, 90% interval 0.4 to 0.6. The upper end of that interval is the gene's LOEUF score, 0.6, which puts it in group 2 of 6, group 1 being the genes least tolerant of losing a copy. Missense variants: 2,828 observed, 3,063.9 expected, observed/expected ratio (o/e) 0.92, 90% interval 0.89 to 0.95. Synonymous variants: 1,168 observed, 1,256.4 expected, observed/expected ratio (o/e) 0.93, 90% interval 0.88 to 0.98.
Homologues: Orthologues: chimpanzee ZFHX2 (99% identical), macaque ZFHX2 (97% identical), guinea pig ZFHX2 (89% identical), pig ZFHX2 (88% identical), dog ZFHX2 (88% identical), rabbit ZFHX2 (86% identical), mouse Zfhx2 (84% identical), rat Zfhx2 (84% identical), tropical clawed frog zfhx2 (42% identical), zebrafish zfhx3a (34% identical), Drosophila melanogaster zfh2 (21% identical), Caenorhabditis elegans zfh-2 (16% identical). Paralogues in human: ZFHX3 (37% identical), ZFHX4 (36% identical), LHX6 (4% identical), LMX1B (4% identical), LMX1A (4% identical), LHX1 (3% identical), LHX2 (3% identical), LHX8 (3% identical), LHX9 (3% identical), LHX5 (3% identical), LHX3 (3% identical), LHX4 (3% identical), and 8 more.
Diseases named in the same sentence as ZFHX2 in open-access papers:
ZFHX2 is named in the same sentence as 14 diseases in open-access papers, as found by Europe PMC text mining. Sharing a sentence is not in itself a finding about the gene and the disease. The quoted sentences say what the papers report.
Anxiety (4 papers, 2012 to 2023). Intense feelings of nervousness, tension, or panic often arise in response to interpersonal stresses. "The time spent by the mutant mice in the center area of the open field was significantly longer than that spent by the control mice throughout the test period, which indicated a reduced anxiety-like phenotype of the Zfhx2-deficient mice." (PMID 23300874, 2012). "Homozygous Zfhx2-deficient mice showed several behavioral abnormalities, namely, hyperactivity, enhanced depression-like behaviors, and an aberrantly altered anxiety-like phenotype." (PMID 23300874, 2012). "In this study, we found that Zfhx2 deficiency caused multiple behavioral abnormalities in mice, namely, hyperactivity, enhanced depression-like behavior, and anxiety-related abnormalities." (PMID 23300874, 2012). "Zfhx2-deficient mice showed increased depression-like behavior and anxiety-like phenotypes." (PMID 37623249, 2023). "Among the DEGs associated with MMS was Zfhx2 (Zinc Finger Homeobox 2), which plays a role in neuronal differentiation and is expressed in sensory neurons; abnormalities in Zfhx2 associate with behavioural abnormalities including hyperactivity and anxiety." (PMID 34589738, 2021). "Zfhx2 was cloned in 2006 and a global knockout mouse was reported in 2012, showing several behavioural abnormalities, namely, hyperactivity, enhanced depression-like behaviours, and an aberrantly altered anxiety-like phenotype." (PMID 29253101, 2018). "The anxiety-related phenotype of the Zfhx2 mutant mice was complicated." (PMID 23300874, 2012). "We presume that each test that we conducted may have assessed separate aspects of the anxiety-related phenotype of the Zfhx2 mutant mice." (PMID 23300874, 2012).
depression (3 papers, 2012 to 2023). "The homozygous Zfhx2 deficient mice showed several behavioral abnormalities particularly in emotional aspects, such as a depression-like phenotype." (PMID 23300874, 2012). "The Zfhx2-deficient strain may serve as a novel model of depression, although several questions remain to be resolved including relationships among various phenotypes observed in the mutant mice." (PMID 23300874, 2012).
Cognitive impairment (1 paper, 2021). Abnormal cognition is characterized by deficits in thinking, reasoning, or remembering. "DYNLRB1 was found to be associated to neuronal survival, INPP5K was found to be associated to cognitive impairment, ZFHX2 was found to be associated to behavioral abnormalities and CTNND2 was found to be associated to mental retardation and intellectual disability." (PMID 33510859, 2021).
gastric cancer (1 paper, 2021). A primary or metastatic malignant neoplasm involving the stomach. "The transcriptional repressor zinc finger homeobox 2 (ZHX2) is reported to regulate tumor progression in several human cancers, although little is known about its role in gastric cancer (GC)." (PMID 33837660, 2021).
Marsili syndrome (1 paper, 2018). "In summary, genetic analysis of a human family with Marsili syndrome, a rare and perhaps unique inherited pain insensitive phenotype, and mouse modelling have shown ZFHX2 as a critical gene for normal pain perception." (PMID 29253101, 2018).
neuroblastoma (1 paper, 2018). Neuroblastoma (NB) is the most common solid, extracranial childhood tumor. "The microarray analyses were complemented by ChIP-seq experiments in human neuroblastoma cells stably expressing the mutant ZFHX2 protein." (PMID 29253101, 2018). "To verify that these AG-rich motifs are present in ZFHX2 DNA-binding regions we used human neuroblastoma SH-SY5Y cells expressing V5-tagged mutant ZFHX2 for ChIP-seq analysis." (PMID 29253101, 2018).
peripheral neuropathy (1 paper, 2018). A disorder affecting the peripheral nervous system. "ZFHX2 has enriched expression within DRGs, particularly within the peripherin positive population of neurons, and so we investigated if the pain insensitive phenotype was due to a peripheral neuropathy." (PMID 29253101, 2018).
psychiatric disorder (1 paper, 2012). A disorder characterized by behavioral and/or psychological abnormalities, often accompanied by physical symptoms. "In this paper, we report the behavioral phenotypes of the Zfhx2-deficient mice and discuss their possible relevance to human psychiatric disorders." (PMID 23300874, 2012). "Moreover, considering their phenotypes, the Zfhx2-deficient mice may provide a novel model of human psychiatric disorders." (PMID 23300874, 2012).
ZFHX2 also shares sentences with these, for which no sentence is quoted: tumor (4 papers); cancer (3); bacterial infection (1); Intellectual disability (1); Obesity (1); staphylococcus aureus infection (1).